TUG1 (taurine up-regulated 1)
Diseases named in the same sentence as TUG1 in open-access papers (continued):
Sharing a sentence is not in itself a finding about the gene and the disease.
melanoma (13 papers, 2019 to 2024). A malignant, usually aggressive tumor composed of atypical, neoplastic melanocytes. "In order to clarify the significance of HOTIAR, MEG3 and TUG1 (family), it would be advisable to conduct an analysis on a large population of melanoma patients and healthy patients, both in tumor tissue and serum." (PMID 38601651, 2024). "A reduced expression in the serum of patients was also shown for the TUG1 (family) lncRNA in the current analysis, while results published so far show its increased expression in melanoma cell lines." (PMID 38601651, 2024). "The available literature showed that inhibition of TUG1 (family) function resulted in inhibition of melanoma cell growth, as well as their ability to metastasize (tested using heterotransplantation in animal models)." (PMID 38601651, 2024). "Another study showed the oncogenic role of TUG1 by enhancing the astrocyte elevated gene-1 (AEG1) expression by sponging miR-129-5p in human malignant melanoma." (PMID 37533667, 2022). "Activation of this regulatory axis leads to an increase in the rate of apoptosis through downregulation of Bcl-2 and upregulation of cleaved caspase -3 in TUG1-suppressed melanoma cells." (PMID 37533667, 2022). "TUG1 is overexpressed in melanoma and promotes tumor growth and metastasis formation in model systems by sponging miR-129-5p and miR-29c-3p." (PMID 35159386, 2022). "Increased expression of lnc-TUG1 in melanoma promoted tumor growth and metastasis by regulating the TUG1/miR-129-5p/AEG-1 and TUG1/miR-29c-3p/RGS1 ceRNA regulatory axis." (PMID 33194692, 2020). "However, knockdown of TUG1 inhibited the growth and metastasis of melanoma cells by regulating miR-29c-3p and its target gene RGS1, as well as inducing apoptosis." (PMID 36601121, 2022). "Two melanoma studies displayed an association between upregulated TUG1 and poor prognosis, with no statistical significance." (PMID 33747256, 2021). "Moreover, the over-expression of the lncRNA Taurine-Upregulated Gene 1 (TUG1) in melanoma tissues and cell lines correlates with poor prognosis." (PMID 33503876, 2021). "This study found that there was a positive correlation between lnc-TUG1 in melanoma and NK cells resting, suggesting that lnc-TUG1 highly expressed in melanoma may mediate the inactivation of immune surveillance and immune clearance." (PMID 33194692, 2020). "In melanoma cells, RGS1 can also be regulated by lncRNA taurine upregulated 1 (TUG1)/miR-29c-3p to promote the proliferation and invasion and inhibit cell apoptosis." (PMID 35879796, 2022). "Still, until now, no experimental validation has functionally linked TUG1 and UCA1 expression to melanocyte transformation and primary melanoma formation." (PMID 35159386, 2022). "Moreover, inhibition of TUG1 expression can downregulate Bcl-2, MMP-9 and cyclin D1 protein, reduce the growth of tumors in melanoma and improve the chemosensitivity of A375 cells to cisplatin and 5-FU." (PMID 36601121, 2022). "In head and neck neoplasms and malignant melanoma, the expression of TUG1 was not significantly correlated with the survival of tumor patients." (PMID 33747256, 2021). "Second, the prognostic role of TUG1 in head and neck neoplasms and malignant melanoma has not been confirmed." (PMID 33747256, 2021).
Cerebral ischemia (12 papers, 2019 to 2025). Restriction of arterial blood supply to the brain associated with insufficient oxygenation to support the metabolic requirements of the tissue. "In another study, lncRNA Tug1 was shown to contribute to NLRP3 inflammasome-dependent pyroptosis after cerebral ischemia via the miRNA-145a-5p/Tlr4 axis." (PMID 41245147, 2025). "Taurine-upregulated gene 1 (TUG1), implicated in diverse biological processes including cell proliferation, apoptosis, and differentiation, has a poorly understood role in cerebral ischemia–reperfusion injury." (PMID 39595085, 2024). "TUG1 has been previously studied both in vivo and in vitro to confirm its role in promoting apoptosis in cerebral ischemia." (PMID 39595085, 2024). "We aim to describe the potential regulatory role of TUG1 in angiogenesis following cerebral ischemia via modulating miR-26a." (PMID 36330459, 2022). "TUG1 also contributes to cerebral ischemia and reperfusion injury by sponging miR-493-3p or miR-410-3p and activating the JNK and p38 MAPK pathways." (PMID 35982898, 2022). "In addition, in cerebral ischemia-reperfusion injury, TUG1 impairs neuronal mitochondrial autophagy by targeting the TUG1/FBXW7 axis." (PMID 40534867, 2025). "However, inhibition of lncRNA Tug1 after experimental cerebral ischemia led to reduced microglial cell activity, reduced infarct size, and improved neurological outcomes." (PMID 41245147, 2025). "Moreover, TUG1 compromised neuronal mitophagy via targeting TUG1/FBXW7 axis in cerebral ischemia and reperfusion injury." (PMID 35928868, 2022). "Another recent research also reveals that in cerebral ischemia/reperfusion, TET2 demethylated LncRNA TUG1, then subsequently promoted NLRP3 inflammasome and contributed to the inflammatory response." (PMID 36527131, 2022).
asthma (11 papers, 2020 to 2024). "In further in vitro experiments on macrophages treated with house dust mites, they demonstrated that TUG1 could regulate B7-H3 expression in macrophages by sponging miR-29c, which then controls Th2 differentiation, providing novel potential diagnostic biomarkers and therapeutic targets for asthma." (PMID 35769905, 2022). "Lin reported that the lncRNA TUG1 promoted airway smooth muscle cell proliferation and migration, contributing to asthma." (PMID 35501805, 2022). "TUG1 downregulation inhibited PDGF-BB-induced HASMC proliferation and migration by regulating miR-216a-3p/SMURF2 axis, offering novel insight into the potential application of TUG1 for childhood asthma treatment." (PMID 34749662, 2021). "Agreement with this report, we observed that TUG1 expression was enhanced in whole blood samples of childhood asthma patients and HASMCs stimulated with PDGF-BB." (PMID 34749662, 2021). "We found that lncRNA TUG1 and B7-H3 were up-regulated in children with asthma exacerbation, and miR-29c was down-regulated compared to controls." (PMID 34335559, 2021). "And we observed that there was inversive correlation between miR-216a-3p level and TUG1 expression in whole blood samples of childhood asthma patients." (PMID 34749662, 2021). "In this study, we examined the role of long non-coding RNA taurine upregulated 1 (lncRNA TUG1) in asthma." (PMID 34335559, 2021). "The level of TUG1 was enhanced 3.34-fold in whole blood samples of childhood asthma patients relative to healthy controls." (PMID 34749662, 2021). "We aimed to explore more effects and molecular mechanism of taurine upregulated gene 1 (TUG1) in childhood asthma." (PMID 34749662, 2021). "Nevertheless, the precise mechanism by which TUG1 influences childhood asthma is not completely understood." (PMID 34749662, 2021). "The TUG1/miR-216a-3p/SMURF2 axis was proposed to provide a novel theoretical basis for childhood asthma treatment." (PMID 34749662, 2021). "In this study, we further examined the role of lncRNA TUG1 in asthma pathogenesis, including Th2 and Th17 cell differentiation." (PMID 34335559, 2021). "A recent study found the role of lncRNA TUG1 in promoting Th2-cell differentiation in asthma." (PMID 35794862, 2022). "TUG1, a 6.7 kilobase (kb) RNA sequence, played critical roles in asthma." (PMID 34749662, 2021). "However, further studies should be conducted to verify the effect of LncRNA TUG1 and miR-29c as therapeutic targets in terms of the experimental asthma model in vivo." (PMID 34335559, 2021). "LncRNA TUG1 and B7-H3 decreased in the convalescent phase compared to acute exacerbation, while miR-29c increased in the convalescent-phase (P < 0.05), which presumed that lncRNA TUG1/miR-29c/B7-H3 axis participates in the asthma exacerbation." (PMID 34335559, 2021). "Interestingly, FGF1 upregulation by the lncRNA TUG1/miR-590-5p axis was found to accelerate proliferation and migration of airway smooth muscle cells and the consequent asthma development." (PMID 33994863, 2021). "This suggests that lncRNA TUG1 may be involved in the acute attack of asthma." (PMID 35794862, 2022). "To further examine whether lncRNA TUG1, miR-29c, and B7-H3 participate in asthma exacerbation, we measured the expression of lncRNA TUG1, miR-29c, and B7-H3 in the peripheral blood collected from 10 children with asthma exacerbation and in the convalescent phase." (PMID 34335559, 2021). "Collectively, these data suggested that TUG1 might be involved in childhood asthma progression." (PMID 34749662, 2021). "Our data indicated that TUG1 might play a critical role in childhood asthma." (PMID 34749662, 2021). "TUG1 and SMURF2 were overexpressed and miR-216a-3p was downregulated in childhood asthma patients and PDGF-BB-stimulated HASMCs." (PMID 34749662, 2021).
asthma (continued). "In rat airway SMCs, the upregulated lncRNA TUG1 and GAS5 act as sponges of miR138-5p and miR10a, respectively, and the lncRNA BCYRN1 increases the stability of the transient receptor potential 1 (TRPC1) protein, thereby promoting the proliferation and migration of airway SMCs in asthma." (PMID 39595622, 2024). "TUG1, serving as the molecular sponge of miR-138-5p, miR-590-5p, miR-216a-3p, and miR-181b, has been confirmed to be involved in ASMC proliferation and migration in human asthma by modulating E2F transcription factor 3 (E2F3), fibroblast growth factor 1 (FGF1), Smurf2 and HMGB1, respectively." (PMID 35769905, 2022).
ischemic stroke (11 papers, 2018 to 2024). A stroke disorder caused by obstruction of blood flow to the brain, due to thrombotic (local blood clot formation) or embolic (due to a blood clot or other material traveling from another site) event. "In ischemic stroke, the rs2240183 C allele of taurine-upregulated gene 1 (TUG1) enhances the risk by enabling the binding of the transcription factor GATA-1, thereby elevating TUG1 expression." (PMID 39595085, 2024). "Concurrently, TUG1 aggravates neuronal apoptosis and necroptosis by sequestering miR-204 and miR-145 in ischemic stroke, thereby modulating apoptosis and inflammatory responses to promote further neuronal damage." (PMID 39595085, 2024). "Through a series of experiments, including gene knockout, histological assessments, and behavioral tests, we aimed to uncover the protective role of TUG1 silencing in ischemic stroke, potentially offering new therapeutic avenues targeting lncRNAs." (PMID 39595085, 2024). "The functional role of lncRNA TUG1 in ischemic stroke has been extensively explored through different mechanisms across various studies highlighting its involvement in neuronal damage and apoptotic pathways." (PMID 39595085, 2024). "Our study reveals a neuroprotective role of the long non-coding RNA TUG1 in ischemic stroke, specifically by reducing neuronal apoptosis through the inhibition of HuR nucleocytoplasmic translocation." (PMID 39595085, 2024). "This study explored the possible regulatory effect and potential mechanisms of TUG1 on angiogenesis following ischemic stroke." (PMID 36330459, 2022). "Previous studies have demonstrated that TUG1 plays an essential role in various ischemic stroke-related procedures." (PMID 36330459, 2022). "Our results regarding the upregulation of TUG1 in diabetic patients who had stroke are in line with recent studies showing that TUG1 was overexpressed in ischemic stroke by regulating miR-9 and decreasing Bcl-2-like 11 protein." (PMID 35237654, 2021). "Recently, studies have found that lncRNAs TUG1, SNHG14, H19, Gm4419, and 1810034E14Rik are associated with the prognosis of ischemic stroke by regulating cell apoptosis and inflammation." (PMID 34707480, 2021). "Taurine‐upregulated gene 1 (TUG1), a kind of long non‐coding RNAs (lncRNAs), was up‐regulated in ischaemic stroke (IS) with the function of promoting neuron apoptosis." (PMID 31264779, 2019). "The elucidation of the roles of TUG1 and HuR in apoptosis not only enhances our understanding of the molecular underpinnings of ischemic stroke but also lays the groundwork for developing therapeutic strategies targeting HuR, potentially improving outcomes and quality of life for stroke patients." (PMID 39595085, 2024). "TUG1 knockout reduces ischemic damage and neuronal apoptosis by inhibiting HuR nucleocytoplasmic shuttling, making TUG1 a potential therapeutic target for ischemic stroke." (PMID 39595085, 2024). "TUG1/miR-26a, which may act as a regulatory axis in angiogenesis following ischemic stroke, can be considered a potential target for cerebral infarction therapy." (PMID 36330459, 2022). "TUG1 rs2240183 may be used as a new biomarker to predict the short-term prognosis of patients with ischemic stroke." (PMID 36330459, 2022). "We intended to determine the effect of TUG1 on angiogenesis following an ischemic stroke." (PMID 36330459, 2022). "Multiple studies reported differential expression of lncRNAs H19, GAS5, PVT1, TUG1, and MALAT1 in ischemic stroke." (PMID 39766887, 2024). "Other lncRNAs, such as ANRIL, SNHG14, TUG1, and MEG3, were also found to affect neuronal apoptosis, inflammation and angiogenesis during ischemic stroke." (PMID 35677353, 2022).
ischemic stroke (continued). "Taurine-upregulated gene 1 (TUG1), an lncRNA, is correlated to ischemic stroke." (PMID 36330459, 2022). "The role and mechanism of TUG1 in angiogenesis following ischemic stroke have not been verified in human tissue samples." (PMID 36330459, 2022). "However, the potential effect of TUG1 on angiogenesis after ischemic stroke is not fully clarified." (PMID 36330459, 2022).
multiple myeloma (11 papers, 2015 to 2025). "Given the previous detection of TUG1 from human serum samples in patients with multiple myeloma, we explored its expression in Friedreich's ataxia serum samples." (PMID 38846537, 2024). "They showed a dysregulation of plasma lincRNA-p21 levels in CLL patients and taurine upregulated gene 1 (TUG1), metastasis associated lung adenocarcinoma transcript 1 (MALAT1), HOX transcript antisense RNA (HOTAIR) and GAS5 in multiple myeloma patients." (PMID 33593440, 2021). "As for the role of lncRNA TUG1 in hematologic malignancy, lncRNA TUG1 is indicated to be involved in the progression and development of several malignancies, such as multiple myeloma (MM) and chronic lymphocytic leukemia." (PMID 34251066, 2021). "The evaluation of lncRNAs expression in plasma samples from leukemia and multiple myeloma showed that TUG1, MALAT1, HOTAIR and GAS5 are more highly expressed in leukemia than in the control samples, and only lincRNA-p21 is upregulated in multiple myeloma." (PMID 25338714, 2015). "TUG1 has been identified in the nuclei of multiple myeloma cells, which aligns with our findings." (PMID 39465506, 2025). "Isin and colleagues reported that several circulating LncRNAs including TUG1, LincRNA-p21, MALAT1, HOTAIR, and GAS5 could be the potential biomarkers for diagnosis of chronic lymphocytic leukemia (CLL) and multiple myeloma (MM)." (PMID 26221732, 2015).
small cell lung carcinoma (11 papers, 2017 to 2020). Small cell lung cancer (SCLC) is a highly aggressive malignant neoplasm, accounting for 10-15% of lung cancer cases, characterized byrapid growth, and early metastasis. "It has been reported that the TUG1 plays a role in promotion of cell growth and drug resistance in small cell lung cancer (SCLC) via regulation of LIMK2b by EZH2 binding." (PMID 31956395, 2020). "For instance TUG1 has a role in induction of chemoresistance in small cell lung cancer cells through regulation of LIMK2b expression." (PMID 33330110, 2020). "Chromatin immunoprecipitation (ChIP) and RNA binding protein immunoprecipitation (RIP) were performed to confirm the molecular mechanism of TUG1 involved in cell growth and chemoresistance of small cell lung cancer." (PMID 28069000, 2017). "It is important to also consider, however, that a recent study documents the involvement of TUG1 in promoting cell growth and chemoresistance in small cell lung cancer." (PMID 29147069, 2017). "TUG1 was the only lncRNA described as downregulated in NSCLC tumor tissues and upregulated in Small Cell lung cancer (SCLC) tissues and the serum of LUAD patients." (PMID 32438606, 2020).
osteoporosis (10 papers, 2020 to 2025). A condition of reduced bone mass, with decreased cortical thickness and a decrease in the number and size of the trabeculae of cancellous bone (but normal chemical composition), resulting in increased fracture incidence. "TUG1 might be a potential target for treating osteoporosis and preventing radiation-induced bone loss." (PMID 39156986, 2024). "LncRNA TUG1, as one of lncRNAs, exerts as an imperative role in several human diseases, such as osteoporosis, cardiomyocyte ischemia, and recent researches have demonstrated its implication in the carcinogenesis of several tumors." (PMID 34251066, 2021). "Plasma lncRNA TUG1 was regulated at a higher level in patients with osteoporosis than in healthy participants." (PMID 33322579, 2020). "A patient with osteoporosis and a healthy patient is distinguished by increasing the regulation of plasma lncRNA TUG1." (PMID 33322579, 2020). "Long non-coding RNA taurine upregulated gene 1 (TUG1), which plays an effective role in the development of human cancers; ankylosing spondylitis, etc., is also shown to be involved in osteoporosis." (PMID 33281877, 2020). "In the plasma of patients of both genders at various stages of osteoporosis, there was upregulation of lncRNA TUG1." (PMID 32664424, 2020). "This study suggests that TUG1 might be a potential target for treating osteoporosis and other bone-related disorders by promoting bone formation." (PMID 39156986, 2024). "TUG1 might be a potential therapeutic target for promoting bone regeneration in periodontal diseases and treating osteoporosis and other bone-related disorders by promoting bone formation." (PMID 39156986, 2024). "TUG1, which influences bone cell development and mineralization, may affect osteoporosis and other bone diseases." (PMID 39156986, 2024). "LncRNA TUG1 plays a crucial role in several human disorders, including osteoporosis and cardiomyocyte ischemia, and recent studies have shown that it may also play a role in the development of many malignancies." (PMID 36428545, 2022). "EGCG up-regulates TUG1 to inhibit the Hippo/YAP pathway activity caused by TNF-α and to improve biological functions of MC3T3-E1 cells, suggesting EGCG can effectively alleviate TNF-α-caused adverse effects in osteoporosis." (PMID 35358011, 2022). "lncRNA TUG1 (taurine-upregulated gene 1) is thought to be upregulated in osteoporosis." (PMID 32664424, 2020). "This suggests that TUG1 might be a potential target for treating osteoporosis." (PMID 39156986, 2024). "Our findings revealed the critical role of the lncRNA TUG1/miR‐34a/FGFR1 axis in FSS‐regulated osteoblast proliferation and apoptosis and may establish potential therapeutic strategies against osteoporosis." (PMID 34350720, 2021). "Taken together, our study revealed the key role of the lncRNA TUG1/miR‐34a/FGFR1 axis in FSS‐regulated osteoblast proliferation and apoptosis and may provide potential therapeutic targets for osteoporosis." (PMID 34350720, 2021). "Therefore, our findings uncovered the role of the lncRNA TUG1/miR‐34a/FGFR1 axis in FSS‐regulated osteoblast proliferation and apoptosis and may provide promising therapeutic strategies for osteoporosis." (PMID 34350720, 2021).